ITGA4 (integrin subunit alpha 4)
Diseases named in the same sentence as ITGA4 in open-access papers (continued):
Sharing a sentence is not in itself a finding about the gene and the disease.
plasmacytoma (2 papers, 2022). Plasmacytoma is a localized mass of neoplastic monoclonal plasma cells that represents approximately 5% of all plasma cell neoplasms. "Both Itga4 (α4) KO 5TGM1-GFP clones KO1 and KO2 demonstrated increased propensity (37%, 6/16) to form extramedullary plasmacytomas in the skin, subcutaneous, and intraperitoneal areas." (PMID 34996933, 2022).
acute GVHD (1 paper, 2021). "Finally, we also examined HDO-mediated Itga4 regulation in acute GVHD model." (PMID 34937876, 2021).
acute kidney failure (1 paper, 2024). "This aligns with our discovery that ITGA4 exhibits a protective effect against acute renal failure in the presence of RAAS inhibitors in DN." (PMID 38332893, 2024). "Among the targets of RAAS inhibitors, PTGS2, ITGA4 and ANPEP have a causal relationship with acute kidney injury, which is worthy of further clinical research." (PMID 38332893, 2024).
acute myeloid leukemia (1 paper, 2023). Acute myeloid leukemia (AML) is a group of neoplasms arising from precursor cells committed to the myeloid cell-line differentiation. "METTL3-mediated m6A modification induces the chemo-resistance in acute myeloid leukemia (AML) cells by increasing the stability of integrin subunit alpha 4 (ITGA4) mRNA." (PMID 36835633, 2023).
adrenocortical carcinoma (1 paper, 2022). "Mesothelioma and stomach adenocarcinoma displayed a higher expression profile for the COL1A1, COL5A1, ITGA4, and EMILIN1, in comparison to adrenocortical carcinoma and kidney renal papillary cell carcinoma." (PMID 35739492, 2022). "However, the hazard ratios remained zero with the stepwise addition of ITGA4, EMILIN1, and TSPAN9 to the Cox model in adrenocortical carcinoma, kidney renal papillary cell carcinoma, and mesothelioma." (PMID 35739492, 2022).
arrhythmogenic right ventricular cardiomyopathy (1 paper, 2017). "The two differentially expressed genes ITGA4 and ITGB8 are present in heart disease-related pathways, including Dilated Cardiomyopathy (DCM), Arrhythmogenic Right Ventricular Cardiomyopathy (ARVC), and hypertrophic cardiomyopathy (HCM)." (PMID 28692647, 2017).
bladder cancer (1 paper, 2025). "The results revealed that bladder cancer cells secrete SPP1, which may interact with the integrin α4/β1 (ITGA4/ITGB1) complex of T cells to influence T cell function." (PMID 40665335, 2025).
breast sarcoma (1 paper, 2015). A malignant mesenchymal neoplasm that arises from the breast. "ITGA4 also promotes colony formation, drug resistance, and tumor-initiation in breast sarcomas." (PMID 26056562, 2015).
breast tumors (1 paper, 2021). "For the only gene among listed, ITGA4, abnormal hypermethylation is not correlated with CIMP, but is strongly correlated with high levels of HER2 expression in breast tumors." (PMID 33500458, 2021).
cervical intraepithelial neoplasia (1 paper, 2025). "A panel of six methylation markers (ASTN1, DLX1, ITGA4, RXFP3, SOX17, ZNF671; GynTect® assay) has shown promise in diagnosing cervical intraepithelial neoplasia (CIN)." (PMID 40022051, 2025).
chordoma (1 paper, 2023). Chordomas are rare malignant tumors arising from embryonic remnants of the notochord in axial skeleton. "Our analysis revealed that the interaction between FN1 and CD44, as well as the interaction between FN1 and ITGA4/ITGB1, plays prominent roles in the communication network of both primary and recurrent chordomas." (PMID 37784253, 2023).
cyst (1 paper, 2017). A sac-like closed membranous structure that may be empty or contain fluid or amorphous material. "However, cyst-lining epithelial cells in Pkd1-deficient kidneys showed reduced and disorganized actin cytoskeletons with significantly decreased levels of marker genes such as Wasf2, Dock1, and Itga4." (PMID 29074972, 2017). "In addition, knocking down Wasf2, Dock1, or Itga4 promoted cyst growth with actin cytoskeleton defects in 3D culture conditions." (PMID 29074972, 2017). "Integrin alpha 4 (Itga4), which we identified as a novel target of miR-182-5p, may play a crucial role in migratory events and we showed that it can affect cyst growth rate in vitro." (PMID 29074972, 2017). "However, miR-182-5p inhibition could not slow cyst growth in Pkd2f/f:Aqp2-cre mice because Wasf2, Dock1, and Itga4 play significant roles in Pkd1 but not in Pkd2 conditional KO mice." (PMID 29074972, 2017).
dysplasia (1 paper, 2025). A usually neoplastic transformation of the cell, associated with altered architectural tissue patterns. "Five of the six markers (ASTN1, ITGA4, RXFP3, SOX17, and ZNF671) showed good positivity in vulvar dysplasia but with unexpected high positivity in VLSIL (VIN I) FFPE samples compared to higher dysplasia grades." (PMID 40022051, 2025).
Familial adenomatous polyposis (1 paper, 2022). Familial adenomatous polyposis (FAP) is characterized by the development of hundreds to thousands of adenomas in the rectum and colon during the second decade of life. "Conversely, DNA hypermethylation of Integrin subunit alpha 4 (ITGA4) has previously been associated with CRC in data generated on peripheral blood mononuclear cells, as well as in familial adenomatous polyposis colon organoids." (PMID 36612042, 2022).
gastric tumors (1 paper, 2022). "The hazard ratio of CAF infiltration in COL1A1, COL5A1, ITGA4, EMILIN1, and TSPAN9 signature was even higher, presenting a 36.8 times higher risk of death in gastric tumors with high CAF infiltration." (PMID 35739492, 2022). "Among the signature genes we identified in this study, targeting the COL1A1, COL5A1 and ITGA4 may have a therapeutic potential in gastric tumors with high CAF infiltration." (PMID 35739492, 2022).
glaucoma (1 paper, 2020). Increased pressure in the eyeball due to obstruction of the outflow of aqueous humor. "ITGA4 is also a high‐risk gene in glaucoma and shows a down‐regulated tendency in glaucoma." (PMID 31680442, 2020). "All these results showed that CD9/ITGA4/PI3K‐Akt axis can mediate apoptosis activity to attenuate glaucoma." (PMID 31680442, 2020). "Furthermore, rescue experiment validated that CD9/ITGA4/PI3K‐Akt axis mediated TM cell apoptosis in glaucoma." (PMID 31680442, 2020). "Results showed that ITGA4 is also shown a down‐regulated tendency in glaucoma." (PMID 31680442, 2020). "Interestingly, in our filter results, we found 2 genes (CD9 and ITGA4) had a great potential to function in glaucoma." (PMID 31680442, 2020). "Thus, whether CD9 can participate in glaucoma via ITGA4 and downstream pathways is proposed by our study." (PMID 31680442, 2020). "Interestingly, we found 8 genes (FN1, THBS1, EPHB2, FGF2, DAB2, CD9, PLAUR and ITGA4) were crucial, suggesting that these genes might function as key factors in the pathogenesis of glaucoma." (PMID 31680442, 2020). "CD9 is down‐regulated in glaucoma, overexpression of CD9 can active integrin α4 (ITGA4), PI3K and Akt, which lead to the decreased apoptosis of TM cell and maintained the TM cell identity." (PMID 31680442, 2020). "CD9 is down‐regulated in glaucoma, overexpression of CD9 can active integrin α4 (ITGA4), PI3K and Akt, which lead to the decreased apoptosis and attenuate glaucoma." (PMID 31680442, 2020). "In glaucoma, overexpression of CD9 can activate expression of ITGA4, phosphorylated PI3K, and Akt, which lead to the inactivation of apoptosis." (PMID 31680442, 2020).
Hyperglycemia (1 paper, 2020). An increased concentration of glucose in the blood. "Taken together, these data suggest that SELL, ITGA4, ARHGAP35, CLDN15 may be closely associated with β-cell autoimmunity in patients with LADA, and the increase of other genes in LADA may only reflect the hyperglycemia status." (PMID 33391182, 2020).
interstitial lung disease (1 paper, 2023). A diverse group of lung diseases that affect the lung parenchyma. "Studies have found that ITGA4 is a crucial regulatory gene in the pathological process of systemic sclerosis-associated interstitial lung disease, which is associated with lung function." (PMID 37772261, 2023).
leiomyosarcoma (1 paper, 2018). An uncommon, aggressive malignant smooth muscle neoplasm, usually occurring in post-menopausal women. "Of these 59 tumours, six GISTs, five leiomyosarcomas and one synovial sarcoma showed high ITGA4 expression at immunohistochemistry." (PMID 29377440, 2018). "Weak ITGA4 expression was present in five GISTs, 16 leiomyosarcomas, two synovial sarcomas and three undifferentiated pleomorphic sarcomas." (PMID 29377440, 2018). "Besides GIST, strong ITGA4 expression was present frequently in four (10.5%) of 38 undifferentiated pleomorphic sarcomas, in eight (26.7%) of 30 leiomyosarcomas and four (23.5%) of 17 synovial sarcomas." (PMID 29377440, 2018). "Interestingly, leiomyosarcomas had a similar ITGA4 expression pattern as GISTs." (PMID 29377440, 2018).
liver fibrosis (1 paper, 2025). "The promotional effect of ITGA4 on these markers counteracted the inhibitory impact of PAE, underscoring ITGA4’s role in exacerbating hepatic fibrosis." (PMID 40103586, 2025). "Our previous work established that ITGA4 mediates the inhibitory effects of Periplaneta americana extract (PAE) on carbon tetrachloride-induced hepatic fibrosis in rats." (PMID 40103586, 2025). "This study delves into ITGA4’s role in the PAE-mediated attenuation of hepatic fibrosis in TGFβ-stimulated LX2 and HSC-T6 cells to elucidate the interaction between ITGA4 and the suppression of LF by PAE." (PMID 40103586, 2025). "This research delves deeper into the potential involvement of ITGA4 in hepatic fibrosis and examines the suppressive effects of PAE on HSC." (PMID 40103586, 2025). "Using TGFβ-induced HSCs, we investigated PAE’s inhibitory effects on hepatic fibrosis and the role of ITGA4 in this process." (PMID 40103586, 2025). "In conclusion, our findings demonstrate ITGA4’s role in PAE-mediated inhibition of hepatic fibrosis, positioning ITGA4 as a potential target for preventing hepatic fibrosis." (PMID 40103586, 2025). "Building on our earlier findings, we observed that ITGA4 expression was significantly elevated in cases of hepatic fibrosis prompted by carbon tetrachloride in rats, but this expression was notably decreased following treatment with PAE." (PMID 40103586, 2025). "ITGA4 could promote liver fibrosis by promoting hepatic stellate cell value-addition, migration, and collagen expression." (PMID 40103586, 2025). "While the specific relationship between ITGA4 and liver fibrosis remains unclear, there is extensive research on the integrin family in this context." (PMID 40103586, 2025). "We hypothesize that ITGA4 is also involved in the PAE-mediated inhibition of inflammatory responses in liver fibrosis (LF)." (PMID 40103586, 2025). "This suggests PAE may inhibit liver fibrosis primarily through suppressing ITGA4." (PMID 40103586, 2025). "This study further explores the relationship between ITGA4 and PAE’s inhibition of hepatic fibrosis." (PMID 40103586, 2025). "However, this study did not explore whether ITGA4 could reverse the inhibition of inflammatory factor expression in hepatic fibrosis by PAE." (PMID 40103586, 2025).
Lymph Node Metastasis (1 paper, 2022). "In this study, we found that high expression of ITGA4 was significantly associated with vascular invasion and lymph node metastasis." (PMID 36254221, 2022). "DCA analysis showed that the prognosis model had an acceptable predictive value in predicting the death risk in 2 years and 3 years, ITGA4 C − index = 0.623 (0.577-0.669), the lymph node metastasis rate C − index = 0.647 (0.593-0.702), and the combined C − index = 0.705 (0.656-0.753)." (PMID 36254221, 2022). "Multivariate Cox regression analysis found that ITGA4 (P = 0.045) and lymph node metastasis rate (P = 0.026) were independent prognostic factors." (PMID 36254221, 2022). "We started with the clinicopathological characteristics of patients and took the pathological characteristics of lymph node metastasis as a separate variable to screen out the abnormal expression of ITGA4 in tumor with positive lymph node metastasis." (PMID 36254221, 2022). "Multivariate Cox regression analysis found that ITGA4 (P = 0.045) and lymph node metastasis rate (P = 0.026) were independent prognostic factors and could construct a prognosis model." (PMID 36254221, 2022). "Chi-square analysis showed that ITGA4 was mainly related to T classification (P = 0.028), N classification (P = 0.006), lymph node metastasis rate (P = 0.018), and serum CA19-9 (P = 0.003), which was basically consistent with the results of previous transcriptome level analysis." (PMID 36254221, 2022). "In this study, we first found that ITGA4 was highly correlated with lymph node metastasis in GC." (PMID 36254221, 2022).
osteoporosis (1 paper, 2025). A condition of reduced bone mass, with decreased cortical thickness and a decrease in the number and size of the trabeculae of cancellous bone (but normal chemical composition), resulting in increased fracture incidence. "Identifying 8 key genes as potential regulatory target genes for the differentiation of mesenchymal stem cells into osteoblasts or adipocytes under the condition of disuse osteoporosis (ITGB3, LAMC1, COL6A3, ITGA8, PDGFRB, ITGA4, LAMB1, LAMA4)." (PMID 40130165, 2025).
peripheral nerve injury (1 paper, 2015). Injury to a peripheral nerve. "Integrin 4α (ITGA4) is a receptor that is expressed after peripheral nerve injury, binds to fibronectin, and is important for neuron regeneration and cell-matrix interactions during leukocyte recruitment." (PMID 26321909, 2015).
sarcoma (1 paper, 2018). A usually aggressive malignant neoplasm of the soft tissue or bone. "ITGA4 expression (either low or high) was detected also in other types of sarcomas, but much less frequently than in GISTs (61 [52.1%] out of 117, P = 0.0009)." (PMID 29377440, 2018). "Similarly, high tumour ITGA4 expression was also more frequent in GISTs in comparison with other sarcomas examined (16 [28.6%] out 56 versus 16 [13.7%] out of 117, P = 0.018)." (PMID 29377440, 2018). "Expression of the ITGA4 protein was next investigated with immunohistochemistry on a sarcoma TMA." (PMID 29377440, 2018).
schwannoma (1 paper, 2013). A benign, usually encapsulated slow growing tumor composed of Schwann cells. "Both states, as well as schwannomas, exclusively overexpress α4-integrin (ITGA4, 1.8-fold, p= 0.003), AP2a (TFAP2A, 1.41-fold, p= 0.009) and Ncad (CDH2, 4.5-fold, p=5.42e-4)." (PMID 23354516, 2013).
skin tumors (1 paper, 2025). "In addition, we observed a higher expression of PD-1 (encoded by Pdcd1), Itga4, Sell, and Ccl5 in skin tumors." (PMID 40282557, 2025). "Consistent with its enhanced immunosuppressive role, Tregs in skin tumors presented higher levels of Itga4, Sell, and Ccl5." (PMID 40282557, 2025).
stomach adenocarcinoma (1 paper, 2022). "Further investigation revealed that the expression of ITGA4 increases with stage in stomach adenocarcinoma." (PMID 35739492, 2022). "Despite that, adding TSPAN9 to the COL1A1, COL5A1, ITGA4, and EMILIN1 Cox model further increased the hazard ratio to 36.813 for CAF infiltration in stomach adenocarcinoma samples." (PMID 35739492, 2022). "All this data suggested COL1A1, COL5A1, ITGA4, EMILIN1, and TSPAN9 as a poor prognostic CAF signature with high specificity to stomach adenocarcinoma." (PMID 35739492, 2022). "This was in parallel to the increase in the poor prognostic impact of CAF infiltration by stage in stomach adenocarcinoma, suggesting a stage and CAF dependent role for ITGA4, EMILIN1, and TSPAN9." (PMID 35739492, 2022). "ITGA4 expression poorly correlated with the CAF infiltration, but the correlation was slightly higher in kidney renal papillary cell carcinoma and stomach adenocarcinoma." (PMID 35739492, 2022). "With further analysis, we revealed COL1A1, COL5A1, ITGA4, EMILIN1, and TSPAN9 as a poor prognostic gene signature for CAF infiltration, with high specificity to stomach adenocarcinoma." (PMID 35739492, 2022). "Based on the comparative pan-cancer analysis of these key CAF markers and a comprehensive literature search we identified COL1A1, COL5A1, ITGA4, EMILIN1, and TSPAN9 as the signature genes, which potentiated the poor prognostic impact of CAF infiltration specifically in stomach adenocarcinoma." (PMID 35739492, 2022). "The KM-survival analysis did not indicate a prognostic role for ITGA4, EMILIN1, or TSPAN9 in stomach adenocarcinoma per se." (PMID 35739492, 2022).
type 2 diabetes (1 paper, 2020). "We further measured and compared the gene expression of CXCR1, SELL, ITGA4, ITGAM, NCF4, ARHGAP3, and CLDN15 in neutrophils from 5 type 2 diabetes patients within 1 year from diagnosis and 5 age- and sex-matched healthy control subjects." (PMID 33391182, 2020).
Vestibular schwannoma (1 paper, 2013). A vestibular schwannoma (also known as acoustic neuroma, acoustic neurinoma, or acoustic neurilemoma) is a benign, usually slow-growing tumor that develops from the VIIIth cranial nerve supplying the inner ear. "MET and associated genes, such as integrin, alpha 4 (ITGA4)/B6, PLEXNB3/SEMA5 and caveolin-1 (CAV1) showed a clear deregulation in vestibular schwannomas." (PMID 23354516, 2013). "Our findings also demonstrate that the MET signaling pathway, which is possibly enhanced by the upstream signaling of SPP1, ITGA4/B6, PLEXNB3/SEMA5A and CAV1, appears to play a paramount role in the development and maintenance of vestibular schwannoma." (PMID 23354516, 2013).